SIRT1 (sirtuin 1)
Diseases named in the same sentence as SIRT1 in open-access papers (continued):
Sharing a sentence is not in itself a finding about the gene and the disease.
Obesity (591 papers, 2008 to 2026). Accumulation of substantial excess body fat. "In conclusion, our results demonstrated that RAGE deficiency improved anti-oxidant properties and prevents adipocyte senescence via the SIRT1 signalling pathway, highlighting a potential therapeutic target for obesity-associated tissue dysfunction." (PMID 41510997, 2026). "Given the metabolic role of SIRT1, further comprehensive investigations in larger longitudinal cohorts are needed to support plasma SIRT1 as an eligible diagnostic tool for stratifying metabolic risk associated with fat mass expansion in obesity." (PMID 42075052, 2026). "The NAD+-dependent deacetylase Sirtuin 1 (SIRT1) plays an essential role in energy metabolism and inflammation and is a promising target to tackle obesity and associated comorbidities." (PMID 40760244, 2025). "Increased levels of miR-34a-3p in obesity are linked to reduced SIRT1, insulin resistance, and metabolic disorders." (PMID 40699679, 2025). "This study demonstrates that the RRTFB improves alleviates obesity and its associated metabolic complications through epigenetic regulation of the DNMT3a/SIRT1/PPARγ axis." (PMID 40909259, 2025). "By inhibiting PPARγ, SIRT1 prevents excessive adipose tissue expansion and reduces inflammation associated with obesity." (PMID 39857404, 2025). "In individuals with obesity, there is a reduction in SIRT1 expression which leads to a loss of its protective functions, including antioxidative properties." (PMID 41011644, 2025). "Despite its positive association with obesity under calorie excess, visfatin reportedly improves longevity by enhancing cell survival and SIRT1 activity, as well as through its neuroprotective effects." (PMID 38672227, 2024). "Firstly, this was intentionally a morphological study, considering the large body of evidence in the literature on molecular characterization of SIRT1-deficient mice (KO or heterozygous) with dietary-induced obesity and in vitro cardiomyocytes." (PMID 38255934, 2024). "miR-377, which acts as a significant regulator of adipogenesis, negatively regulates SIRT1 by targeting its mRNA, resulting in the development of both inflammation caused by obesity and insulin resistance." (PMID 38892574, 2024). "Hypothalamic SIRT1 levels increased in models of pubertal undernutrition, bound to pubertal delay, whereas conditions of early obesity, linked to accelerated puberty, were associated with decreased SIRT1 content in the hypothalamus." (PMID 39290326, 2024). "With regard to alternate mechanisms for nerve regeneration, sirtuin-1 (SIRT-1) inactivation has been implicated in obesity and neurodegeneration and SIRT-1 activation is associated with nerve regeneration following peripheral nerve injury." (PMID 38974580, 2024). "This study aimed to evaluate global histone acetylation status and SIRT1 gene expression in children and adolescents with obesity and their association with metabolic and anthropometric parameters." (PMID 37862340, 2023). "There is further evidence suggesting a connection between obesity and cognitive function through alterations in DNA methylation of memory-associated genes, particularly SIRT1 within the hippocampus." (PMID 38026693, 2023). "By elucidating the association between SIRT1 expression, histone acetylation, and obesity, our study highlights the significance of epigenetic modifications in obesity and its accompanying insulin resistance." (PMID 37862340, 2023). "One possibility was that there was a strong correlation between obesity, body mass index (BMI), and SIRT1 gene polymorphisms." (PMID 36789048, 2023). "Maize extract rich in ferulic acid and anthocyanins prevents HFD-induced obesity in mice by modulating Sirtuin 1 (SIRT1)/AMP-activated protein kinase (AMPK)/IL-6 associated metabolic and inflammatory pathways." (PMID 37063272, 2023). "SIRT1 has been recognized as one of the protective factors against pathological conditions linked to obesity by regulating autophagy and cell death." (PMID 37627494, 2023).
Obesity (continued). "Circulating SIRT1 is negatively associated with fat mass, leptin, and insulin resistance, and positively associated with adiponectin, an “anti-obesity” hormone." (PMID 37679377, 2023). "The downregulation of the Sirt-1 gene is associated with many diseases, including type II diabetes and obesity." (PMID 37512578, 2023). "The authors indicate that SIRT1 plays a central role in the pathogenesis of obesity-linked memory impairment and that administration of a SIRT1 activator (resveratrol) averts the manifestation of memory impairment in obese mice." (PMID 37432552, 2023). "Myeloid cell Sirtuin 1 (SIRT1) has been shown to play a protective role in studies of metabolic diseases caused by obesity." (PMID 37153549, 2023). "For example, exosomes play a pivotal role in adipose Sirt1 deficiency-mediated obesity and insulin resistance." (PMID 35502767, 2022). "SIRT1 is a caloric restriction mimetic that has been associated with improved longevity and a reduction in age-related complications (such as T2D and obesity)." (PMID 35889827, 2022). "We recently reported that plasma SIRT1 is inversely associated with NAFLD severity in a cohort of patients with obesity." (PMID 35956321, 2022). "This phenotype is observed, also, in humans, in which the reduced expression of SIRT1 enhances the differentiation capacity of VAT-derived stem cells, fostering VAT expansion, and the reduction of SIRT1 mRNA transcription in VAT is associated with obesity." (PMID 36555502, 2022). "Anti-aging gene sirtuin 1 is possibly associated with the nature of the diet that targets the underlying mechanisms with relevance to diet- and obesity-induced cognitive impairment and neurodegenerative diseases." (PMID 35873818, 2022). "SIRT1 exerts its activity primarily in response to a reduced caloric intake, and in patients with obesity, its plasma concentrations increase with fat loss." (PMID 35956321, 2022). "Some SIRT1 gene variations are associated with waist circumference (WC) and the waist–hip ratio in men with obesity." (PMID 35956321, 2022). "Altered levels of SIRTs genes have been observed in the adipose tissue of individuals with obesity, indicating that a fat increase changes the expression of genes encoding SIRT1." (PMID 35956321, 2022). "Of note, both obesity and aging have been associated with a fall in SIRT1 activity in AT, which in turn has been related to aberrant inflammation." (PMID 35811457, 2022). "Sirtuin 1 (SIRT1)-mediated inhibition of Kiss1 is a key epigenetic mechanism associated with nutrition and obesity in mammalian puberty." (PMID 36776772, 2022). "The underlying molecular mechanism of celastrol anti-obesity and increase the leptin sensitivity can be attributed to Sirtuin 1(Sirt1), interleukin-1 receptor 1(IL1R1), protein tyrosine phosphatase (PTP) 1B (PTP1B), and T-cell PTP (TCPTP)." (PMID 35444532, 2022). "Vascular dysfunction of DIO mice can be normalized by ex vivo incubation with NAD+, indicating a causal role of NAD+ deficiency in obesity-induced vascular dysfunction and the therapeutic potential of stimulating SIRT1 activity by improving NAD+ levels." (PMID 35326191, 2022). "In humans, the reduction in SIRT1 mRNA transcription in visceral adipose tissue (VAT) is associated with obesity and hepatic steatosis." (PMID 35956321, 2022). "Several studies have shown that adipose tissue responds to energy shortage with specific activation of SIRT1, and that patients with severe obesity who experienced weight loss have a significant induction of SIRT1 expression in SAT." (PMID 36555502, 2022). "SIRT1 function is aberrantly low in obesity; therefore, understanding the underlying mechanisms is important for drug development." (PMID 35277012, 2022).
Obesity (continued). "Sirtuins are key metabolic sensors involved in the pathophysiology of inflammatory‐related processes including aging and obesity, and both obesity and aging have been associated with a reduction in SIRT1 activity in AT." (PMID 35811457, 2022). "For example, resveratrol has been shown to protect mice from diet-induced obesity and insulin resistance, cause improved mitochondrial function, and prevent metabolic diseases by activating SIRT1." (PMID 36479179, 2022). "Although previous studies have shown that some of the Sirt1 SNPs are associated with glucose tolerance, obesity, body fat and blood pressure, there are very few studies of Sirt1 gene SNPs and MetS in a Chinese Han population." (PMID 35365152, 2022). "Herein, FRD decreased the SIRT1 protein level in the rat heart, in line with the findings that MetS, obesity, and chronic inflammation have been associated with reduced levels of SIRT1." (PMID 33976753, 2021). "Sirt1‐overexpression in mice reduced the susceptibility to HFD‐induced obesity and hepatic steatosis, which is consistent with the results of this study." (PMID 33159388, 2021). "It was also found that miR-200c directly downregulates SIRT1, which has a significant role in protection from obesity and associated comorbidities." (PMID 34690698, 2021). "SIRT1 also improves obesity-associated metabolic diseases through deacetylating and activating mitochondrial biogenetic marker, PGC-1α." (PMID 33935745, 2021). "The combination of quercetin with resveratrol suppresses obesity-associated inflammation in rats induced by a high-fat diet via AMPKα1/SIRT1 signaling pathway." (PMID 34394985, 2021). "SIRT1 plays an important role in tissues linked with fat metabolism, including visceral fat; therefore, it can be a master target gene for management of obesity and related diseases." (PMID 34578872, 2021). "The agent metformin, an inhibitor of mTOR activity, can prevent such processes during obesity in experimental mouse models and can reverse the loss of SIRT1 function during inhibition of the circadian components CLOCK and BMAL1." (PMID 34590471, 2021). "A decreased SIRT1 activity in the hippocampus during obesity is caused by circulating palmitic acid, which lowers SIRT1 activity through NAD+ depletion." (PMID 33806509, 2021). "Our recent study confirmed that resveratrol upregulated SIRT1 expression to ameliorate vascular dysfunction associated with diabetes and obesity." (PMID 34348746, 2021). "In contrast, mice fed a high-fat diet show a loss of SIRT1 via proteolysis and obesity can lower the expression of SIRT1 in humans." (PMID 33398091, 2021). "Accordingly, the specific inhibition of SIRT1 in SF1 neurons makes HFD fed mice more susceptible to obesity and diabetes mellitus." (PMID 33572672, 2021). "Many rodent and human studies showed that impairment of hepatic SIRT1 signaling was closely associated with obesity and ALD." (PMID 33994911, 2021). "SIRT1 has been implicated in obesity, insulin resistance, type 2 diabetes mellitus and fatty liver disease." (PMID 34899339, 2021). "The SIRT1 enzyme is involved in metabolic processes and stress resistance, and its dysregulation is linked to obesity and diabetes development." (PMID 34017061, 2021). "The genetic impairment of Sirt1 in POMC neurons causes hypersensitivity to diet-induced obesity due to reduced energy expenditure and compromises the remodelling of white adipose tissue." (PMID 33573212, 2021). "Excessive fat accumulation inhibits AMPK/SIRT1 activation in obese rodents, which aggravates obesity-associated metabolic complications." (PMID 34684660, 2021). "SIRT1 has been associated with obesity and is involved in food intake regulation, life span, diabetes, and CVD." (PMID 32982666, 2020). "These trainings are considered as one of the obesity prevention and treatment strategies in addition to a cost-effective protocol for increasing SIRT1, PGC-1α, CAT, weight loss and fat loss in obese individuals." (PMID 32586268, 2020).
Obesity (continued). "Deficiency of SIRT1 in obesity leads to elevated inflammation characterized by increased mRNA expression of NFκB and pro-inflammatory cytokines in white adipose tissue." (PMID 32971941, 2020). "Genetic or pharmacological Sirt1 inhibition can induce insulin resistance (IR), and genetic Sirt1 variations have been associated with human energy expenditure and obesity." (PMID 32933003, 2020). "Recent studies showed that single nucleotide polymorphisms (SNPs) in the SIRT1 gene are associated with carotid atherosclerosis, major depressive disorder, age-related macular degeneration, and severe obesity." (PMID 32188057, 2020). "AMPK-deficient mice fed a high-fat diet to induce obesity exhibited increased body weight and fat mass and decreased SIRT1 expression in adipose tissues." (PMID 32899992, 2020). "In adipose tissue-specific Sirt1-deficienct mice, the obesity-induced brown-to-white transition of PVAT is exaggerated in vivo, which augments endothelial dysfunction." (PMID 33050331, 2020). "Several genetic polymorphisms of SIRT1 have also been shown to be associated with different health conditions, such as metabolic disorders (obesity, hyperglycemia and hypertension) and chronic inflammatory states." (PMID 30714469, 2019). "Phosphorylation of SIRT1 by JNK1 primes SIRT1 for ubiquitination and degradation, and persistent JNK1 activation in obesity causes severe hepatic SIRT1 degradation." (PMID 30116482, 2018). "SIRT2, far less studied than SIRT1, is emerging as distinctly important in obesity and inflammation, including obesity associated with sepsis." (PMID 30216989, 2018). "Although the specific mechanisms by which the RES-associated gut microbiota exerts its anti-obesity-promoting activity remain to be identified, Sirt1 signaling appears to be a key pathway associated with this process in diet-induced obese mice." (PMID 30567366, 2018). "In these models, increased NAD levels activated the SIRT1–PGC1α axis and prevented the metabolic disorders that are associated with aging and obesity." (PMID 29901258, 2018). "Here, we provide an overview of the association of the increasing level of SIRT1 protein for regulating some disease related conditions such as obesity, cardiovascular diseases and neurodegeneration." (PMID 30374331, 2018). "Several metabolic disorders such as liver steatosis, diabetes, and obesity associate with defects in SIRT1 pathways." (PMID 30131769, 2018). "To explore the molecular mechanisms underlying CD38 deficiency‐mediated inhibition of obesity, we detected the protein expression levels of Sirt1 and the target gene PPARγ which was known to promote adipocyte differentiation." (PMID 28816006, 2018). "The miR-377/SIRT1 pathway is implicated as a potential target for attenuating the inflammatory state in adipocytes during obesity." (PMID 29050301, 2017). "Accumulating evidence suggests that two important nutrient sensors and inflammatory regulators, AMPK and SIRT1, act as pathogenic factors for adipocyte formation and adipose tissue inflammation and macrophage infiltration during the development of obesity." (PMID 28353634, 2017). "AMPK/Sirt1 activation reduced obesity-associated macrophage infiltration and inflammation in adipose tissue." (PMID 28640832, 2017). "As discussed, obesity with chronic inflammation and the metabolic syndrome are associated with reduced levels of SIRT1." (PMID 26904696, 2016). "Subsequently, several single nucleotide polymorphisms (SNPs) located in SIRT1 had been tested for their association with obesity and metabolic syndrome components." (PMID 27104517, 2016). "Apart from the case-control studies testing the effect of SIRT1 polymorphisms on genetic predisposition to obesity, there is also evidence for an association of different SIRTs SNPs with prevalence of obesity-related complications." (PMID 27104517, 2016).
Obesity (continued). "An association study of SIRT1 gene variations with visceral obesity found that the rs7069102 C allele was associated with reduced risk of obesity in Belgian Caucasians." (PMID 25706717, 2015). "In spite of several SIRT1 polymorphism studies on BMI, obesity, diabetes and cardiovascular diseases, there is a few number of SIRT1 SNPs studies on life span longevity in humans." (PMID 25785999, 2015). "We believe that a better understanding of the interrelationship between SIRT1 and mTOR signaling will promote the development of new pharmacological insights to treat metabolic diseases associated with obesity." (PMID 25330910, 2014). "In line with this, it has been shown that polymorphisms in the SIRT1 gene are related to an increased body mass index and increased risk of obesity." (PMID 23880847, 2013). "Genetic variants of the SIRT1 gene have been shown to be associated with human diabetes and obesity-related phenotypes in several previous studies, while only a few genetic association studies for the SIRT1 gene and lipid metabolism have been reported." (PMID 23305113, 2013). "It has been demonstrated that decreased activity of SIRT1 is associated with metabolic diseases such as obesity and type 2 diabetes." (PMID 23226517, 2012). "Above information suggests that Sirt1 is involved in regulation of obesity-associated metabolic diseases through regulating PGC-1α, UCP2 and LXR proteins." (PMID 21549004, 2011). "Fasting leads to the up-regulation of SIRT1 in adipose tissue of mice, pigs and humans whereas decreased SIRT1 expression is associated with obesity." (PMID 22115311, 2011). "In the present study, we characterize the early molecular signaling mechanisms potentially underlying the therapeutic efficacy of SIRT1 activation by small molecules in a diet induced obesity model." (PMID 19284563, 2009). "In obese, SIRT1 expression in adipose tissue was significantly suppressed, and downregulation of SIRT1 May contribute to obesity-associated metabolic abnormalities." (PMID 41510997, 2026). "A quercetin and resveratrol blend’s obesity-reducing effects are linked to its anti-inflammatory properties; it decreases adipokine secretion, activates AMPKα1/SIRT1 signaling, and thus may reduce HFD-induced obesity and inflammation." (PMID 40732979, 2025). "There are SIRT1-dependent biochemical pathways linked to obesity and adipogenesis." (PMID 41567643, 2025). "Sirtuins, particularly SIRT1, are associated with metabolic diseases such as obesity and diabetes." (PMID 39871746, 2025). "Importantly, dietary weight loss has been shown to restore SIRT1 levels, indicating that obesity modulates its expression." (PMID 41376865, 2025). "Similarly, other studies in preclinical models have demonstrated a role for adipose tissue SIRT1 in protecting against metabolic damage associated with obesity." (PMID 40760244, 2025). "Consequently, SIRT1 and PPARγ have emerged as promising therapeutic targets for managing male infertility associated with obesity and metabolic syndrome." (PMID 41445731, 2025). "This suggests that dysregulated insulin signaling could be the predisposing factor leading to the inhibition of the Sirt1-Pgc1a-Ucp2 axis, adipocyte dysfunction, and the eventual development of obesity and insulin resistance with age." (PMID 38891115, 2024). "As such, reduced enzymatic activity of SIRT1 has been mechanistically linked to numerous age-related diseases such as Alzheimer, Parkinson, type 2 Diabetes, Metabolic syndrome, and Obesity." (PMID 38790038, 2024). "The genetic variant SIRT1 rs3818292 has been linked to obesity and MetS." (PMID 39858569, 2024). "The reduction of SIRT1 will cause metabolic disorders, fatty liver and obesity." (PMID 36632457, 2023).